TNFSF11 (TNF superfamily member 11)
Diseases named in the same sentence as TNFSF11 in open-access papers (continued):
Sharing a sentence is not in itself a finding about the gene and the disease.
tumor (continued). "Interestingly, in a mouse melanoma model, the combination of antibodies against TNFSF11 and CTLA4 inhibits tumor growth and metastasis, accompanied by increased T-cell effector function due to significantly higher T-cell infiltration into the tumor." (PMID 37828948, 2023). "Whereas Tnfsf11 expression in tumour tissue was increased by the two calcitriol analogues, RANKL was not affected at the protein level in tumour tissue but was increased by PRI-2191 in the plasma (p=0.0889)." (PMID 31595196, 2019). "Interestingly, in the tumours from mice treated with PRI-2191 and PRI-2205, the expression of Tnfsf11 (RANKL) was increased." (PMID 31595196, 2019). "In addition, the member genes FGF19, GAS2, BMP7, TNFSF11, and FGFR3 are all known to play important roles in tumor genesis and progression." (PMID 22863767, 2012).
cancer (353 papers, 2003 to 2026). A tumor composed of atypical neoplastic, often pleomorphic cells that invade other tissues. "Malignant tumors usually cause osteolysis, a process featuring classic ligand-receptor interactions between OC and osteoblastic OS cells involved in OC formation, such as TNFSF11-TNFRSF11A." (PMID 34367994, 2021). "In our study, we employed the TIMER database to scrutinize TNFSF11 expression across various cancer types." (PMID 38594779, 2024). "TNF receptor superfamily member 11a (RANK) and its ligand TNF superfamily member 11 (TNFRSF11, RANKL) have also been linked to cancer." (PMID 38902257, 2024). "Despite this, the comprehensive expression pattern of TNFSF11 (RANKL) across various types of cancer and its relationship with clinicopathological parameters remains largely unexplored." (PMID 38594779, 2024). "TNFRSF11B and TNFSF11 were also incorporated into our analysis because of their importance in the regulation of bone metabolism and cancer cell invasiveness." (PMID 36011038, 2022). "TNFSF11 encodes receptor activator nuclear factor-κB ligand (RANKL), which is frequently expressed by cancer cells." (PMID 32872487, 2020). "TNFSF11, initially recognized as a crucial regulator of bone metabolism via the RANK/RANKL/OPG pathway, has been increasingly implicated in the progression of various cancers, as well as in their tendency to undergo epithelial-mesenchymal transition." (PMID 38594779, 2024). "TNFSF11, also named RANKL, is a critical regulator for cancer bone metastases." (PMID 35978854, 2022). "Moreover, TNFSF11 is targeted by two FDA approved cancer drugs, it is selected only by MVSPL and SPL." (PMID 31534156, 2019). "To comprehensively understand these three lncRNAs (BOLA3-AS1, AC124067.4, and AL161772.1) and four target RNAs (NINL, SALL4, TNFSF11, PHYHIPL), we performed differential expression, cancer stemness, immune subtype, TME infiltration, and drug sensitivity analyses." (PMID 34746134, 2021).
infection (83 papers, 2012 to 2026). The state of being infected such as from the introduction of a foreign agent such as serum, vaccine, antigenic substance or organism. "Since we found that Tnfsf11 mRNA was significantly higher in “severe” and “minor” patients, we speculate that in HAdV-55 infection, RANKL is up-regulated in reactive T cells, B cells and macrophages, and the RANKL expression level is positively associated with the infection severity." (PMID 30787914, 2019). "We found that the expression of eight genes, including Il18, Il36b, Il17rc, Tnfsf10, Tnfsf11, Tnfsf14, Tnfsf15, and Il1a, were closely correlated with the severity of HAdV-55 infection." (PMID 30787914, 2019). "In support of studies reporting increased susceptibility to infection with AUD, we report down-regulation of a number of genes important for host defense such as cytokines (IL1R1 and TNFSF11), chemokines (CCL2), and receptors (TGFBR1 and TLR8)." (PMID 27427759, 2016). "Additionally, TNFSF11 and TNFSF15 was expressed at lower levels after infection." (PMID 31725732, 2019).
immune diseases (5 papers, 2007 to 2024). "Hence, ASD-induced decreases in peripheral blood CCL19 and TNFSF11 levels may further exacerbate immune system disorders." (PMID 38742104, 2024).
TNFSF11 also shares sentences with these, for which no sentence is quoted: periodontal disease (94 papers); postmenopausal osteoporosis (80); multiple myeloma (78); Osteopenia (72); bone metastasis (47); melanoma (41); bone tumors (37); Hypercalcemia (37); bone disorder (34); osteonecrosis (34); Insulin resistance (33); Obesity (30); Peri-Implantitis (30); giant cell tumor (27); Hyperglycemia (27); cardiovascular disease (23); chronic periodontitis (23); type 2 diabetes (23); sarcopenia (20); apical periodontitis (18); heart failure (17); osteomyelitis (17); bacterial infection (16); Hypertension (16); Hypocalcemia (16); inflammatory bone diseases (15); metastasis (15); endothelial dysfunction (14); inflammatory bowel disease (14); colitis (13).
A further 417 diseases each share a sentence with TNFSF11 in 13 papers or fewer.